ANP32E (acidic nuclear phosphoprotein 32 family member E)
Diseases named in the same sentence as ANP32E in open-access papers (continued):
Sharing a sentence is not in itself a finding about the gene and the disease.
cancer (12 papers, 2017 to 2025). A tumor composed of atypical neoplastic, often pleomorphic cells that invade other tissues. "ANP32e, a chaperone of H2A.Z, is receiving increasing attention because of its association with cancer growth and progression." (PMID 38482865, 2024). "We have shown here that ANP32e is required for proper cell proliferation in the U2OS cancer cell line." (PMID 38482865, 2024). "We confirmed that ANP32e regulates the growth of human U2OS cancer cells and preferentially interacts with H2A.Z during the G1 phase of the cell cycle." (PMID 38482865, 2024). "ANP32e and H2A.Z are thought to play important roles in cell proliferation, cell cycle progression, and cancer." (PMID 38482865, 2024). "Rather, our data suggest that ANP32e is a molecular chaperone required for stabilization of H2A.Z in the cytoplasm following protein synthesis in a cancer context." (PMID 38482865, 2024). "Members of the acidic leucine-rich nucleophosphoprotein 32 (ANP32) family, which mainly includes ANP32A, ANP32B, and ANP32E, are abnormally expressed and have prognostic value in certain cancers." (PMID 35280441, 2022). "Acidic nuclear phosphoprotein 32 family member e (Anp32e) has been reported to contribute to early mammalian development and cancer metastasis." (PMID 36263179, 2022). "ANP32E, an acid nuclear phosphoprotein and a leucine-rich repeat protein family member, has diverse activities in cell adhesion, early mammalian development, and cancer metastasis." (PMID 39968094, 2025). "Moreover, the expression of ANP32E was confirmed in various cancers, and it was discovered that ANP32E exhibited higher expression in COAD tissues than that in the normal tissues." (PMID 38585643, 2024). "ANP32E has been revealed to participate in the progression of different cancers." (PMID 38585643, 2024). "An unanswered question is whether ANP32e regulates H2A.Z dynamics during the cell cycle; this could have clear implications for the proliferation of cancer cells." (PMID 38482865, 2024). "ANP32E has been discovered to participate in a variety of cancers." (PMID 38585643, 2024). "Several studies have investigated the role of ANP32E in cancer development." (PMID 33148205, 2020). "Interestingly, we discovered that ANP32E is a negative prognostic factor, where high ANP32E expression was correlated with high risk of cancer recurrence and distant metastasis." (PMID 29633513, 2018). "Where to put ANP32E in cancer metastasis regulation network remains unknown at this time." (PMID 28220627, 2017). "Considering the significant roles of miR‐141 in inhibiting cell migration and invasion in different cancer types, and the potentially significant effect of ANP32E in cancer cells, we reason that miR‐141 and ANP32E might have some direct interaction in BC cells." (PMID 28220627, 2017). "Acidic nuclear phosphoprotein 32 family member E (ANP32E) belongs to the leucine rich protein family, which is involved in multiple biological processes, such as cell adhesion, early mammalian cell growth, and cancer metastasis." (PMID 38585643, 2024). "Additionally, accumulating evidence has hinted the relationship between acidic nuclear phosphoprotein 32 family member E (ANP32E) and cancer progression." (PMID 38585643, 2024). "Acidic nuclear phosphoprotein 32 family member E (ANP32E) belongs to a family of proteins with leucine‐rich repeats, which involve a large number of biological functions, such as cell adhesion, early mammalian development, and cancer metastasis." (PMID 29633513, 2018).
infection (2 papers, 2017 to 2023). The state of being infected such as from the introduction of a foreign agent such as serum, vaccine, antigenic substance or organism. "In chickens, ANP32E was weakly downregulated in all tissues in response to infection with all subtypes except for H3N8 and H4N6." (PMID 37358408, 2023). "Accordingly, we codepleted ANP32E (92.0 ± 0.1% knockdown on day 5 after infection) with H2A.Z.2 and observed a partial rescue of rapid Arc transcription." (PMID 28856239, 2017).
ANP32E also shares sentences with these, for which no sentence is quoted: acute myeloid leukemia (1 paper); colorectal cancer (1); esophageal cancer (1); gastric cancer (1); lung adenocarcinoma (1); medulloblastoma (1); mesothelioma (1); pancreatic adenocarcinoma (1); systemic lupus erythematosus (1).